DGKE (diacylglycerol kinase epsilon)
Description:
Membrane-bound diacylglycerol kinase that converts diacylglycerol/DAG into phosphatidic acid/phosphatidate/PA and regulates the respective levels of these two bioactive lipids. Thereby, acts as a central switch between the signaling pathways activated by these second messengers with different cellular targets and opposite effects in numerous biological processes. Also plays an important role in the biosynthesis of complex lipids. Displays specificity for diacylglycerol substrates with an arachidonoyl acyl chain at the sn-2 position, with the highest activity toward 1-octadecanoyl-2- (5Z,8Z,11Z,14Z-eicosatetraenoyl)-sn-glycerol the main diacylglycerol intermediate within the phosphatidylinositol turnover cycle. Can also phosphorylate diacylglycerol substrates with a linoleoyl acyl chain at the sn-2 position but much less efficiently.
Synonyms: DAGK5; DAGK6; DGK; AHUS7; NPHS7
Tractability: Antibody: its Gene Ontology location is reachable by antibodies, with high confidence; UniProt predicts a signal peptide or a membrane-spanning region. PROTAC: ubiquitination databases record sites on it; its protein half-life has been measured.
Target class: Enzyme; Transferase
Gene: Protein-coding gene on chromosome 17 (56,834,103 to 56,869,567, forward strand). Ensembl gene ENSG00000153933.
Subcellular location: Membrane; Cytoplasm
Subcellular location (Human Protein Atlas): Cytosol; Nucleoplasm
Pathways (Reactome):
Hemostasis: Effects of PIP2 hydrolysis
Gene Ontology:
Molecular function: ATP-dependent diacylglycerol kinase activity; kinase activity
Biological process: diacylglycerol metabolic process; lipid phosphorylation; phosphatidic acid biosynthetic process; glycerolipid metabolic process; intracellular signal transduction; platelet activation; modulation of chemical synaptic transmission; phosphatidylinositol biosynthetic process; phospholipase C-activating G protein-coupled receptor signaling pathway; phosphorus metabolic process; signal transduction
Cellular component: cytoplasm; cytosol; membrane; plasma membrane; glutamatergic synapse
Genetic constraint (gnomAD): Loss-of-function variants: 49 observed, 62.47 expected, observed/expected ratio (o/e) 0.78, 90% interval 0.62 to 1. The upper end of that interval is the gene's LOEUF score, 1, which puts it in group 4 of 6, group 1 being the genes least tolerant of losing a copy. Missense variants: 605 observed, 667.52 expected, observed/expected ratio (o/e) 0.91, 90% interval 0.85 to 0.97. Synonymous variants: 279 observed, 244.63 expected, observed/expected ratio (o/e) 1.14, 90% interval 1.03 to 1.26.
Gene-disease validity (ClinGen):
ClinGen rates the evidence that DGKE causes each of these diseases.
atypical hemolytic-uremic syndrome with DGKE deficiency (autosomal recessive): Definitive.
membranoproliferative glomerulonephritis (autosomal recessive): Definitive. Inflammation of the glomeruli characterized by deposits at the intraglomerular mesangium, resulting in thickening of the glomerular basement membrane, activation of complement, and impaired kidney function secondary to damaged glomeruli.
Homologues: Orthologues: chimpanzee DGKE (99% identical), macaque DGKE (99% identical), dog DGKE (95% identical), guinea pig DGKE (93% identical), rabbit DGKE (91% identical), mouse Dgke (90% identical), pig DGKE (89% identical), rat Dgke (89% identical), tropical clawed frog dgke (74% identical), zebrafish dgke (69% identical), Drosophila melanogaster CG34384 (34% identical), Caenorhabditis elegans dgk-4 (32% identical), and 2 more. Paralogues in human: DGKD (36% identical), DGKH (35% identical), DGKK (33% identical), DGKQ (33% identical), DGKB (32% identical), DGKG (32% identical), DGKA (31% identical), DGKI (29% identical), DGKZ (29% identical).
Diseases named in the same sentence as DGKE in open-access papers:
DGKE is named in the same sentence as 50 diseases in open-access papers, as found by Europe PMC text mining. Sharing a sentence is not in itself a finding about the gene and the disease. The quoted sentences say what the papers report.
atypical hemolytic-uremic syndrome (7 papers, 2015 to 2024). A rare, genetic thrombotic microangiopathy due to dysregulation of the alternative complement pathway and characterized by the triad of hemolytic anemia, thrombocytopenia, and acute renal dysfunction. "Recessive mutations of DGKε are associated with atypical hemolytic uremic syndrome, a disease characterized by renal vascular endothelial injury due to diminished poly-unsaturated fatty acids, which are required for prostanoid synthesis." (PMID 32962151, 2020). "Additionally, DGKE mutations are associated with atypical hemolytic uremic syndrome (aHUS) and membranoproliferative glomerulonephritis, conditions marked by kidney damage due to microvascular thrombosis." (PMID 39684917, 2024). "Indeed, recessive loss-of-function mutations in DGKε cause atypical hemolytic-uremic syndrome (aHUS)." (PMID 27803897, 2016). "The importance of the biological role of DGKε is suggested by the fact that it is the only DGK isoform that is associated with a human disease, namely atypical hemolytic uremic syndrome (aHUS)." (PMID 27803897, 2016). "Loss of function of the lipid kinase diacylglycerol kinase ε (DGKε), encoded by the gene DGKE, causes a form of atypical hemolytic uremic syndrome that is not related to abnormalities of the alternative pathway of the complement, by mechanisms that are not understood." (PMID 33986189, 2021).
hemolytic-uremic syndrome (7 papers, 2021 to 2026). Acute kidney injury associated with microangiopathic hemolytic anemia and thrombocytopenia. "Atypical haemolytic uraemic syndrome was instead strictly associated to DGKε gene (DGKE) recessive mutations." (PMID 40859612, 2026). "Additionally, given that loss of DGKε is known to cause an atypical hemolytic-uremic syndrome, future work should also investigate whether synthesis of LPA by this enzyme is mechanistically implicated." (PMID 38280449, 2024). "It turns out that the human diacylglycerol kinase epsilon (DGKE) mutation, a cause of the hemolytic uremic syndrome, also reflects inhibition of VEGF signaling and consequent de-differentiation of glomerular EC." (PMID 34912827, 2021).
nephrotic syndrome (4 papers, 2018 to 2025). A collection of symptoms that include severe edema, proteinuria, and hypoalbuminemia; it is indicative of renal dysfunction. "Although those with DGKE variants are known to manifest nephrotic syndrome, we observed severe proteinuria in up to 50% of patients with other genetic abnormalities." (PMID 29511899, 2018). "Finally, mutations in DGKE, encoding diacylglycerol kinase-ε (DGKE) have been linked with infantile-onset aHUS, accompanied by nephrotic syndrome and chronic kidney disease (CKD), through an as yet unresolved mechanism." (PMID 34248927, 2021). "In summary, DGKE mutations display genetic pleiotropy, with the phenotype comprising pathological features of MPGN to different extents, and clinical features of aHUS, nephrotic syndrome, or both." (PMID 32386968, 2020).
Methylmalonic aciduria (3 papers, 2018 to 2025). Increased concentration of methylmalonic acid in the urine. "This includes metabolic screening for methylmalonic aciduria, assessment of ADAMTS13, and genetic testing for variants in the complement regulatory pathway plus DGKE (Diacylglycerol Kinase Epsilon) variants." (PMID 40565949, 2025). "Comprehensive re-testing confirmed the previous results and excluded mutations of diacylglycerol kinase-epsilon (DGKE), plasminogen (PLG) and methylmalonic aciduria and homocystinuria, cblC complementation type (MMACHC), but identified a homozygous deletion of CFHR3/1." (PMID 29728803, 2018).
Obesity (3 papers, 2022 to 2024). Accumulation of substantial excess body fat. "Recently, we have reported that DGKε deficiency promotes adipose tissue remodeling in mice during the course of high fat diet (HFD) feeding regimen including obesity, insulin resistance, and beige adipogenesis." (PMID 35153836, 2022). "DGKε activity can exacerbate seizure susceptibility and contribute to Huntington’s disease through altered PI/PPIn levels, while its deletion may lead to obesity in mice." (PMID 39684917, 2024). "The interest in DGKε is enhanced by the link detected in mouse models between its activity and the development of Huntington’s disease, seizure susceptibility, and protection from obesity." (PMID 38008259, 2023). "DGKε contributes to lipid metabolism preventing obesity, an activity attributed to DGKε located in the endoplasmic reticulum." (PMID 38008259, 2023). "Under short-term (40 days) HFD feeding, a presymptomatic phase of obesity in WT mice, DGKε-KO mice show severe obesity and insulin resistant phenotype, whereas WT mice remain normal." (PMID 35153836, 2022). "DGKε-KO mice exhibit obesity, insulin resistance and beige adipogenesis when fed a high-fat diet." (PMID 39684917, 2024). "It is not so simple because DGKε-KO mice show severe obesity and insulin resistant phenotype under short-term (40 days) HFD feeding conditions." (PMID 35153836, 2022).
thrombotic microangiopathy (3 papers, 2020 to 2023). The syndromes of microangiopathic hemolytic anemia, thrombocytopenia, and variable signs of organ impairment, due to platelet aggregation in the microcirculation. "Atypical hemolytic uremic syndrome (aHUS) with diacylglycerol kinase epsilon (DGKE) gene variant is a rare variant of thrombotic microangiopathy (TMA)." (PMID 37456562, 2023). "In a differential diagnosis, we excluded the mutations in diacylglycerol kinase epsilon (DGKE) gene, whose presence could be responsible for the renal pathology of thrombotic microangiopathy or MPGN and cobalamin C disease, which may also present as HUS with renal TMA during infancy." (PMID 34502390, 2021).
acute kidney injury (2 papers, 2015 to 2026). Sudden and sustained deterioration of the kidney function characterized by decreased glomerular filtration rate, increased serum creatinine or oliguria. "Genetic testing, performed only at the age of 13 years, revealed a homozygous DGKE mutation (c.412T>C; p.C138R), despite a typical presentation, including hemolytic anemia, thrombocytopenia, and acute kidney injury." (PMID 42077707, 2026).
cobalamin C deficiency (2 papers, 2014 to 2024). "Eculizumab’s efficacy is generally not reliant on genetic mutations, as both patients with and without complement gene abnormalities can respond similarly, except in cases involving cobalamin C deficiency or DGKE mutations." (PMID 39507167, 2024). "Some rare genetic variants of HUS, such as DGKE mutations and cobalamin C deficiency, do not affect the complement pathway directly." (PMID 39507167, 2024). "Other causes of idiopathic TMA such as mutations of diacylglycerol kinase epsilon (DGKE) and cobalamin C disease are very rare or have not been described in adults." (PMID 25400666, 2014).
cobalamin deficiency (2 papers, 2021 to 2024). "TMA can also occur in relation to metabolic disorders (e.g., cobalamin deficiency), loss of diacylglycerol kinase epsilon (DGKE), and, perhaps, monoclonal gammopathies." (PMID 34300201, 2021). "Other inherited causes of TMA, independent of complements, include cobalamin deficiency and diacylglycerol kinase epsilon (DGKe) variants." (PMID 39518638, 2024).
epilepsy (2 papers, 2016 to 2018). A brain disorder characterized by episodes of abnormally increased neuronal discharge resulting in transient episodes of sensory or motor neurological dysfunction, or psychic dysfunction. "There are also data suggesting that DGKε may play a role in epilepsy and Huntington disease." (PMID 27803897, 2016).
homocystinuria (2 papers, 2020 to 2021). An autosomal recessive inherited metabolic disorder caused by mutations in the CBS, MTHFR, MTR, and MTRR genes. "Recently, it has been identified that mutation in non-complement genes such as diacylglycerol kinase epsilon (DGKE), thrombomodulin (THBD), inverted formin 2 (INF2) and methylmalonic aciduria and homocystinuria cobalamin C (cbLC) type (MMACHC) can also trigger aHUS." (PMID 32838746, 2020).
Huntington disease (2 papers, 2016 to 2026). Huntington disease (HD) is a rare neurodegenerative disorder of the central nervous system characterized by unwanted choreatic movements, behavioral and psychiatric disturbances and dementia. "DGKε has been identified as a promising target for treating Huntington's Disease (HD)." (PMID 27803897, 2016). "DGKε is also related to neuronal disorders, as its ablation can for instance make neurons resistant to seizures, and it seems to contribute to Huntington's disease, because the negative modulation of DGKε activity prevented for example huntingtin protein activation of caspase‐3." (PMID 40859612, 2026).
kidney failure (2 papers, 2015 to 2023). An acute or chronic condition that is characterized by the inability of the kidneys to adequately filter the blood. "Recessive mutations in DGKE cause small-vessel thrombosis and kidney failure." (PMID 37190222, 2023).
Nephropathy (2 papers, 2016 to 2025). A nonspecific term referring to disease or damage of the kidneys. "Now that work on Dgkε-null mice has potential health-related ramifications (for patients with DGKE-associated nephropathy, See Section Relationship to Disease), it is critical to determine if this model accurately reflects true Dgkε-deficiency." (PMID 27803897, 2016). "Whole-exome sequencing recently uncovered an unexpected link between homozygous mutations in the gene encoding for DGKε and DGKε-associated nephropathy." (PMID 27803897, 2016). "Dgkε-null mice may thus be a promising research tool to further our understanding of DGKε-associated nephropathy (assuming it is a full knockout—see Section Post-translational Modifications of DGKε Proteins)." (PMID 27803897, 2016).
atherosclerosis (1 paper, 2022). A disease characterized by the build-up of fatty material and calcium deposition in the arterial wall resulting in partial or complete occlusion of the arterial lumen. "Furthermore, PTGDS and DGKE may have crucial roles in the progression of CAD atherosclerosis." (PMID 36088434, 2022).
colon cancer (1 paper, 2023). "DGKE was targeted by hsa-miR-3065-5p, which was over-expressed in colon cancer." (PMID 37190222, 2023).
coronary atherosclerosis (1 paper, 2022). Atherosclerosis of the coronary vasculature. "The progression of coronary atherosclerosis may be influenced by genes such as PTGDS and DGKE." (PMID 36088434, 2022).
depressive disorder (1 paper, 2012). A melancholy feeling of sadness and despair. "Among the cognate genes, six including ALG8, DGKE, GNA12, KLF11, LRPAP1, and MMAB are related to multiple genetic diseases such as depressive disorder and Type-II diabetes." (PMID 22348086, 2012).
Hypertension (1 paper, 2023). The presence of chronic increased pressure in the systemic arterial system. "In the same way, plasma therapy did not prevent kidney progression or improve hypertension control in our patient with DGKE variants." (PMID 37456562, 2023).
left ventricular hypertrophy (1 paper, 2016). Enlargement of the LEFT VENTRICLE of the heart. "Decreased DgkE mRNA levels were observed in the hearts of rats used for modeling left ventricular hypertrophy and myocardial infarction." (PMID 27803897, 2016). "When subjected to two distinct protocols known to induce left ventricular hypertrophy in wild type mice, DGKε-overexpressing mice appeared to be protected." (PMID 27803897, 2016).
lung carcinoma (1 paper, 2023). "DGKE and WDR47 were found with significant associations with responses to both systemic therapies and radiotherapy in lung cancer." (PMID 37190222, 2023). "From the list of genes that were targeted by the 73 diagnostic miRNAs, DGKE and WDR47 had significant associations with responses to both systemic therapies and radiotherapy in lung cancer." (PMID 37190222, 2023).
myocardial infarction (1 paper, 2011). Gross necrosis of the myocardium, as a result of interruption of the blood supply to the area, as in coronary thrombosis. "Downregulation of DGKε in rat hearts was observed in both myocardial infarction and aortic banding models." (PMID 21548979, 2011).
tumor (3 papers, 2023 to 2025). "Conversely, DGKε knockdown significantly reduced tumor growth indicating that phosphatidylinositol-dependent signaling is likely required for these tumors." (PMID 40822358, 2025). "Taken together with the results from the drug testing, these data provide evidence that Dgk, but not Dgkε, rdgA or the serotonin receptor genes, is required for Ras-driven polarity-impaired tumour growth." (PMID 36861754, 2023). "These trends are essentially in line with the TCGA results, except for the lack of evidence for increased expression of DGKE and DGKZ in tumor samples." (PMID 37509516, 2023).
cancer (2 papers, 2016 to 2025). A tumor composed of atypical neoplastic, often pleomorphic cells that invade other tissues. "The fact that patients with complete DGKε deficiency do not appear to have increase cancer risks suggests that this mechanism is unlikely to be a primary driver (See Section Relationship to Disease)." (PMID 27803897, 2016). "Differences between the PI-cycles of normal and cancer cells have yet to be thoroughly investigated: we anticipate that the activity of other DGKs and/or CDS enzymes must supplant that of DGKε/CDS2 during oncogeny." (PMID 27803897, 2016). "Indeed, analyses of cancer databases, including The Cancer Genome Atlas, have revealed DGKα, DGKγ, DGKδ, DGKε, and DGKζ overexpression in AML, although without a clear correlation to specific subtypes." (PMID 41227366, 2025).
DGKE also shares sentences with these, for which no sentence is quoted: membranoproliferative glomerulonephritis (3 papers); Insulin resistance (2); kidney disease (2); metabolic disease (2); Thrombocytopenia (2); acute myeloid leukemia (1); Alzheimer disease (1); antiphospholipid antibody syndrome (1); bipolar disorder (1); cardiac hypertrophy (1); chronic kidney disease (1); cobalamin C disease (1); congenital disorder of glycosylation (1); coronary artery disease (1); dyslipidemia (1); genetic diseases (1); glomerulonephritis (1); heart failure (1); Hyperhomocystinemia (1); major depressive disorder (1); microangiopathic hemolytic anemia (1); monoclonal gammopathies (1); renal failure (1); scleroderma (1); thrombotic thrombocytopenic purpura (1); Type-II diabetes (1).